RNU6-883P (RNA, U6 small nuclear 883, pseudogene)
Gene: Small nuclear RNA gene on chromosome 10 (73,529,051 to 73,529,157, reverse strand). Ensembl gene ENSG00000207327.
Homologues: Orthologues: chimpanzee U6 (99% identical), macaque U6 (94% identical), pig U6 (84% identical). Paralogues in human: RNU6-16P (88% identical), RNU6-1 (85% identical), RNU6-1181P (85% identical), RNU6-1263P (85% identical), RNU6-144P (85% identical), RNU6-2 (85% identical), RNU6-247P (85% identical), RNU6-38P (85% identical), RNU6-39P (85% identical), RNU6-3P (85% identical), RNU6-480P (85% identical), RNU6-4P (85% identical), and 1285 more.